RN7SL193P (RNA, 7SL, cytoplasmic 193, pseudogene)
Gene: Miscellaneous RNA gene on chromosome 4 (43,863,274 to 43,863,549, forward strand). Ensembl gene ENSG00000239679.
Homologues: Orthologues: chimpanzee Metazoa_SRP (99% identical). Paralogues in human: RN7SL1 (72% identical), RN7SL2 (72% identical), RN7SL122P (71% identical), RN7SL145P (71% identical), RN7SL493P (71% identical), RN7SL3 (71% identical), RN7SL45P (70% identical), RN7SL660P (70% identical), RN7SL127P (70% identical), RN7SL301P (70% identical), RN7SL57P (70% identical), RN7SL788P (70% identical), and 701 more.